TCF4 (transcription factor 4)
Diseases named in the same sentence as TCF4 in open-access papers (continued):
Sharing a sentence is not in itself a finding about the gene and the disease.
Pitt-Hopkins syndrome (continued). "Pitt-Hopkins syndrome (PTHS, OMIM #610954) is a genetic neurodevelopmental disorder associated with an abnormal expression of the basic helix-loop-helix transcription factor 4 gene (TCF4) located on chromosome 18q21 (OMIM #602272)." (PMID 31586495, 2019). "Pitt-Hopkins Syndrome, associated with mutations in the transcription factor E2-2 (TCF4), although not classified as PID, impairs in-vitro responses of pDCs." (PMID 27755182, 2016). "In four cases, patients’ phenotypes well matched to the syndromic features caused by haploinsufficiency of PAX6 (Aniridia, MIM:607108), TCF4 (Pitt-Hopkins syndrome, MIM:610954), FBN1 (skeletal/joint malformations, limb deformity; MIM:154700), and TWIST1 (Saethre-Chotzen syndrome, MIM:101400)." (PMID 27257017, 2016). "Genes that were part of this signature on the brain side were the TCF4, ATN1, PPP2R2B, ATXN10 and ATXN3, which are associated with neurodegenerative and developmental disorders such as Pitt-Hopkins Syndrome, Dentatorubral pallidoluysian atrophy, SCA12, SCA10 and SCA3." (PMID 27476530, 2016). "The TCF4 gene, which encodes a protein known as transcription factor 4, is one of only two genes in our set to have an MIM number assigned and has been implicated in Pitt-Hopkins Syndrome, a condition that results in severe intellectual and physical disabilities." (PMID 26043920, 2015). "In Pitt-Hopkins syndrome, ATFs could increase expression of wild type TCF4 in cases of TCF4 haploinsufficiency." (PMID 24946931, 2014). "Pitt-Hopkins Syndrome (PHS) is a sporadic condition caused by mutations or deletions of the TCF4 gene on chromosome 18q; patients present with absent speech, seizures and facial features resembling AS, together with a sociable personality." (PMID 20459762, 2010). "Finally, we observed TCF4 upregulation in either of two iPSC lines derived from individuals with Pitt-Hopkins syndrome, following viral delivery of either the TSS-targeting (1.6-fold, q = 8e-5; 1.5-fold; q = 2e-7) or enhancer-targeting (1.2-fold, q = 3e-4; 1.1-fold; q = 0.02) gRNA." (PMID 41278953, 2025). "Our results suggest that miR-495 can target transcription factor 4 (TCF4), a gene linked to the neurodevelopmental disorder Pitt-Hopkins syndrome (PTHS), to ensure normal differentiation of NPCs in the developing cerebral cortex." (PMID 39664574, 2024). "The deletion region contains the TCF4 and SMAD4 genes, whose haploinsufficiency causes the causative genes of Pitt-Hopkins syndrome (PTHS) and juvenile polyposis/hereditary hemorrhagic telangiectasia (JPHT or JPHHT), respectively." (PMID 37521594, 2023). "As the resulting disease is not as severe as the Pitt-Hopkins syndrome, it may mean that a slight decrease in overall TCF4 expression causes the phenotype." (PMID 36407762, 2022). "Importantly however, complete haploinsufficiency of TCF4 is known to result in Pitt-Hopkins syndrome (OMIM # 610954); a severe neurodevelopmental disorder associated with profound intellectual disability, absence of speech, behavioural issues and ventilation abnormalities." (PMID 32735996, 2021). "Rare missense variants and structural variation that disrupt TCF4 cause Pitt-Hopkins syndrome, which is characterized by facial dysmorphism, developmental delay, and autonomic dysfunction and are strong risk factors in ASD; whereas common variation of TCF4 has been robustly associated with SCZ." (PMID 26805891, 2016). "Pitt-Hopkins syndrome (PTHS; MIM# 610954) is a genetically determined entity mainly caused by mutations in TransCription Factor 4 (TCF4)." (PMID 27072915, 2016). "Mutations associated with a genetic disorder known as Pitt-Hopkins syndrome (PTHS), which is characterized by intellectual disability, distinct facial features, developmental delay, and autonomic dysfunction, mostly occur within the bHLH domain of TCF4." (PMID 40149012, 2025).
Pitt-Hopkins syndrome (continued). "Finally, a working diagnosis of Mowat Wilson syndrome was changed to Pitt-Hopkins syndrome in a 2.5-year-old male with severe developmental delay, no speech, microcephaly, poor weight gain and a happy demeanour after a de novo mutation was identified in TCF4 (c.1486G>C, p.(Gly496Arg))." (PMID 31345272, 2019). "Mouse models of Pitt-Hopkins syndrome, lacking functional Tcf4, typically show hyperactivity, reduced anxiety, and deficient spatial and associative learning." (PMID 29933371, 2018).
breast cancer (67 papers, 2009 to 2025). A primary or metastatic malignant neoplasm involving the breast. "In this study, PDX-based modeling of breast cancer chemoresistance leads to the identification of loss of TCF4 as being associated with this phenotype." (PMID 29666142, 2018). "Loss of TCF4 conferred chemoresistance in breast cancer cell models, possibly by altering cell cycle regulation." (PMID 29666142, 2018). "TCF4 has been found to be mutated in variety of tumor types such as renal cell carcinoma, gastric carcinoma and breast cancer." (PMID 24943349, 2014). "Herein, we have provided the evidence that the GL treatment causes significant down-regulation of the TCF-4 protein expression in human breast cancer MCF-7 and MDA-MB-231 cells." (PMID 23914993, 2013). "High levels of OPN and Tcf-4 mRNA expression were significantly associated with survival in breast cancer patients." (PMID 21772333, 2011). "The expression of TCF4 is associated with breast cancer chemoresistance." (PMID 34021255, 2021). "Finally, TCF4 is an important transcription factor, its loss is related with breast cancer chemoresistance." (PMID 30906311, 2019). "Filtering specifically for breast cancer datasets including the risk of metastasis during the first year following treatment, we found correlations between metastatic malignancy and the expression of positive regulators of Wnt/β-catenin signaling (e.g., TCF4)." (PMID 26202299, 2015). "Interestingly, hypermethylation has be implicated in the downregulation of CLDN7 expression in breast cancer and two transcription factors, Tcf-4 and Sox9, have been shown to cooperate in CLDN7 repression in colon cells." (PMID 21789222, 2011). "The involvement of TCF4/β-catenin in regulating GLCE expression was shown also for MCF7 breast cancer cells both in vitro and in vivo." (PMID 39318629, 2024). "AMD1 activates TCF4 translation by enhancing spermidine production and eIF5A hypusination of breast cancer cells, promoting breast cancer aggressiveness." (PMID 38654332, 2024). "TCF4, appointed as a tumor suppressor in breast cancer, was down-expressed intumor samples, especially in non-luminal subtypes (ER-/PR-)." (PMID 38100720, 2023). "HOXB13 is upregulated in breast cancer but exerts a cytostatic effect by negatively regulating the expression of TCF-4 in prostate cancer." (PMID 38203393, 2023). "Regarding the biomarker potential in breast cancer, our resultssuggest that LEF1, TCF3, TCF4, and specially TCF7, have significant diagnostic valueto distinguish breast cancer patients from healthy individuals and a role insubtyping insight." (PMID 38100720, 2023). "Considering that TCF4 is an important oncogene in breast cancer and has a highest score, we therefore selected TCF4 for further verification." (PMID 37096846, 2023). "Despite insufficient evidence, FLT3L/STAT3 cascade directly conducted pDC and anti-tumor immunity via Tcf4 in breast cancer." (PMID 33957948, 2021). "In yet another study, simultaneous inhibition of STAT3 and Tcf4 signaling pathways was reported to suppress the breast cancer cells metastasis both in vitro and in vivo." (PMID 33957948, 2021). "Although it is generally assumed that binding of β-catenin to members of the TCF family is cancer-promoting, recent studies have shown that Tcf4 functions instead as a repressor that restricts the breast cancer cell growth." (PMID 33957948, 2021). "Sox9 has been shown to mediate the Wnt/β-catenin activation through the regulation of LRP6 and TCF4 expression in breast cancer." (PMID 34615853, 2021). "CCAT1/ANXA2/GSK3β activates the WNT/β-catenin signaling pathway by increasing the amount of nuclear β-catenin, which interacts with transcription factor 4 (TCF4), resulting in the migration and invasion of breast cancer." (PMID 33050646, 2020). "TCF4 has been validated to play a role in the regulation of breast cancer-induced bone lesions by β-catenin protein signaling." (PMID 31897234, 2020).
breast cancer (continued). "By upregulating the TCF4 expression, we demonstrated that TCF4 mediated the inhibiting effects of miR-591 expression on cell proliferation and invasion in breast cancer cells." (PMID 31049030, 2019). "miR-204/211 overexpression or LncCCAT1 knockdown significantly repressed the expression of TCF4 protein in breast cancer cells, while miR-204/211 downregulation or LncCCAT1 overexpression upregulated TCF4 protein levels." (PMID 31695775, 2019). "TCF4 mediated the inhibiting effects of miR-591 on cell proliferation and invasion in breast cancer cells." (PMID 31049030, 2019). "The TCF4/β-catenin pathway and chromatin structure cooperate to regulate d-glucuronyl C5-epimerase expression in breast cancer." (PMID 31049030, 2019). "Sox9 is a poor prognostic indicator and is strongly associated with Wnt signaling via LRP6 (Low-density lipoprotein receptor-related protein 6) and TCF4 (Transcription Factor 4) in breast cancer." (PMID 31394796, 2019). "Together, these results from tumor xenograft modeling depict a link between altered TCF4 expression and breast cancer chemoresistance." (PMID 29666142, 2018). "Perhaps, over expression of TCF-4 and CTNNB1 genes were associated with the activation of MAPK gene in breast cancer cell lines with different degrees of invasiveness." (PMID 30379886, 2018). "Although TCF4 was reported to promote cancer cell stemness and metastasis in breast cancer patients and in clear cell renal cell carcinoma, its role in invasive bladder cancer was described to be beneficial, participating in the inhibition of tumor growth." (PMID 30223528, 2018). "Kindlin-2, which regulates Wnt signaling, also regulates β-catenin expression, and forms tripartite transcriptional complex with β-catenin and TCF4 to promote Wnt target gene expression during breast cancer progression." (PMID 27713156, 2016). "Such an assumption is supported by the fact that TCF4 is found at higher levels in normal than in breast cancer tissue in the TCGA set and in another material." (PMID 27809802, 2016). "When analyzed in the context of the PPI network, we observed that TCF4 had a high number of second-order neighbor proteins related to breast cancer." (PMID 26043920, 2015). "In this study, we aim to investigate the regulation of p68 gene expression through β-catenin/transcription factor 4 (TCF4) signaling in breast cancer." (PMID 25499975, 2014). "All these results indicate that p68 upregulation through β-catenin/TCF4 signaling is important for enhanced transactivation of β-catenin target genes and thus attributes to the tumourigenic potential of breast cancer cells." (PMID 25499975, 2014). "Our study further suggests that β-catenin/TCF4 along with c-Myc upregulate p68 in breast cancer cells favouring EMT." (PMID 25499975, 2014). "Canonical Wnt signaling in human colon and breast cancer cells plays a key role for the aberrant activation of the β-catenin/TCF4 in tumour progression." (PMID 25499975, 2014). "The expression of AXIN, DVL1, and TCF4 showed variable levels in different TN breast cancer cell lines." (PMID 24143235, 2013). "The decreased expression of Wnt/β-Catenin targeting genes, such as cyclin D1, C-myc and survivin, and the inhibition of the activity of the transcription factor (T-cell factor 4, TCF-4) were observed in GL-treated breast cancer cells." (PMID 23914993, 2013). "In contrast, overexpression of Tcf-4 in combination with β-catenin in breast cancer cells led to increased expression of monocyte chemotactic protein-1, which promotes cancer progression." (PMID 21772333, 2011). "This highlights the role of other Wnt target genes downstream of Tcf-4 in Tcf-4-modulated cell invasion in breast cancer cells." (PMID 21772333, 2011). "This stimulation took place through the AKT/β-catenin/TCF-4 signaling pathway in breast cancer cells overexpressing the HER2 receptor." (PMID 21689417, 2011).
breast cancer (continued). "In endoderm formation, β-catenin interacts with Sox17 independently of TCF-4 to activate endoderm genes and in breast cancer, β-catenin and Sox2 interact independently of TCF-4 to activate Cyclin D1." (PMID 20811503, 2010). "Recent data also show TCF-4 is lost in human breast cancers and abundant in the surrounding normal tissue, indicating that TCF-4 is a tumor suppressor in this tissue." (PMID 19924301, 2009). "We found that TCF-4 is differentially expressed in cells derived from DMBA-induced mouse mammary tumors from VDR wild-type and knock out mice, and the mammary glands themselves." (PMID 19924301, 2009). "GREB1 expression is regulated by ERα in breast cancer and by TCF4 in hepatoblastoma." (PMID 37658191, 2023). "In addition, FMOD is critical for breast cancer cell migration and invasion and is positively regulated by the β-catenin/TCF4/LEF1 complex." (PMID 36986805, 2023). "In breast cancer, TCF4 is also suggested to playa role in tumor suppression,with low expression of TCF4 being related to chemoresistance inbreast cancer xenograft models via cell cycle deregulation and to metastasis, having its lowexpression accentuated in breast-to-brain metastasis." (PMID 38100720, 2023). "Wnt signalling within adipocytes promotes stemness, as demonstrated in breast cancer where adipocyte-secreted IL-6 and leptin activate breast cancer stem cells through Notch, Wnt, and Sex determining region Y-box 2/octamer binding transcription factor 4/Nanog signalling." (PMID 38136392, 2023). "Let-7 has been reported to activate the WNT signaling pathway via targeting estrogen receptors in breast cancer, and transcription factor 4 (TCF-4; a downstream target of WNT) in hepatocellular carcinoma (HCC), resulting in increased cancer stemness and aggressiveness." (PMID 35164678, 2022). "As such Tcf4 might be used act as a new prognostic biomarker and valuable molecular target for breast cancer immunotherapy." (PMID 33957948, 2021). "Lung cancer cell lines presented a higher expression of TCF4 compared to breast cancer cell lines." (PMID 33917757, 2021). "Previous studies observe that TCF-4 could influence the progression of multiple cancers including lung cancer, hepatocellular cancer, and breast cancer." (PMID 30867651, 2019). "Previous studies have found that LHX6 modulated the carcinogenicity of breast cancer cells via β-catenin/TCF4 complex, we thus speculated that LHX9 might have the similar regulatory function on OS through β-catenin/TCF4 since it was the homologue of LHX6." (PMID 31788020, 2019). "Next, we aimed to assess the functional role of TCF4 using breast cancer cell lines." (PMID 29666142, 2018). "There is also evidence that TCF4 may have a role in breast cancer progression due to its interaction with the β-catenin protein (encoded by the CTNNB1 gene) and the Wnt signaling pathway." (PMID 26043920, 2015). "Interestingly, TCF4 has only one first-order neighbor identified as breast cancer-related, the androgen receptor AR." (PMID 26043920, 2015). "Furthermore, we have shown that p68 being the co-activator of β-catenin is also critically involved in the Wnt signaling-mediated expression of TCF4 in breast cancer cells." (PMID 25499975, 2014). "Thus, β-catenin/TCF4 and p68 constitute a positive feedback loop essential for β-catenin-mediated processes involved in breast cancer progression." (PMID 25499975, 2014). "Therefore, we conclude that the GL-induced apoptotic cell death in human breast cancer cells is regulated by TCF-4." (PMID 23914993, 2013). "However, in breast cancer, paradoxical results for the role of Tcf-4 on cancer progression have been reported." (PMID 21772333, 2011). "Taken together, our results indicate that the functional role of Tcf-4 in breast cancer progression may be determined by Wnt-dependent OPN regulation and expression, and that OPN and Tcf-4 may be used in combination as a novel prognostic indicator." (PMID 21772333, 2011).